MCM5 (minichromosome maintenance complex component 5)
Description:
Acts as a component of the MCM2-7 complex (MCM complex) which is the replicative helicase essential for 'once per cell cycle' DNA replication initiation and elongation in eukaryotic cells. Core component of CDC45-MCM-GINS (CMG) helicase, the molecular machine that unwinds template DNA during replication, and around which the replisome is built. The active ATPase sites in the MCM2-7 ring are formed through the interaction surfaces of two neighboring subunits such that a critical structure of a conserved arginine finger motif is provided in trans relative to the ATP-binding site of the Walker A box of the adjacent subunit. The six ATPase active sites, however, are likely to contribute differentially to the complex helicase activity.
Synonyms: CDC46; MGORS8; P1-CDC46
Tractability: Small molecule: a structure with a bound ligand is known. PROTAC: ubiquitination databases record sites on it; its protein half-life has been measured.
Target class: Enzyme; Hydrolase
Gene: Protein-coding gene on chromosome 22 (35,400,123 to 35,425,431, forward strand). Ensembl gene ENSG00000100297.
Subcellular location: Nucleus; Chromosome
Subcellular location (Human Protein Atlas): Nucleoplasm
Pathways (Reactome):
DNA Replication: Activation of the pre-replicative complex; Assembly of the pre-replicative complex; Orc1 removal from chromatin; Switching of origins to a post-replicative state; Unwinding of DNA
Cell Cycle: Activation of ATR in response to replication stress
Developmental Biology: Regulation of MITF-M-dependent genes involved in DNA replication, damage repair and senescence
Gene Ontology:
Molecular function: protein binding; 3'-5' DNA helicase activity; single-stranded DNA binding; single-stranded DNA helicase activity; ATP binding; ATP hydrolysis activity; DNA binding; DNA helicase activity; DNA replication origin binding
Biological process: DNA replication; DNA replication initiation; double-strand break repair via break-induced replication; regulation of DNA-templated DNA replication initiation
Cellular component: chromosome; chromosome, telomeric region; CMG complex; MCM complex; membrane; nucleoplasm; nucleus
Genetic constraint (gnomAD): Loss-of-function variants: 43 observed, 73.6 expected, observed/expected ratio (o/e) 0.58, 90% interval 0.46 to 0.75. The upper end of that interval is the gene's LOEUF score, 0.75, which puts it in group 3 of 6, group 1 being the genes least tolerant of losing a copy. Missense variants: 867 observed, 1,008.3 expected, observed/expected ratio (o/e) 0.86, 90% interval 0.81 to 0.91. Synonymous variants: 400 observed, 392.87 expected, observed/expected ratio (o/e) 1.02, 90% interval 0.94 to 1.11.
Homologues: Orthologues: chimpanzee MCM5 (99% identical), macaque MCM5 (99% identical), dog MCM5 (98% identical), pig MCM5 (97% identical), mouse Mcm5 (96% identical), rabbit MCM5 (96% identical), rat Mcm5 (94% identical), guinea pig MCM5 (94% identical), tropical clawed frog mcm5 (87% identical), zebrafish mcm5 (81% identical), Drosophila melanogaster Mcm5 (69% identical), Caenorhabditis elegans mcm-5 (62% identical). Paralogues in human: MCM4 (32% identical), MCM3 (32% identical), MCM2 (31% identical), MCM6 (30% identical), MCM7 (28% identical), MCM8 (26% identical), MCM9 (25% identical), MCMDC2 (13% identical).
Diseases named in the same sentence as MCM5 in open-access papers:
MCM5 is named in the same sentence as 88 diseases in open-access papers, as found by Europe PMC text mining. Sharing a sentence is not in itself a finding about the gene and the disease. The quoted sentences say what the papers report.
cervical cancer (15 papers, 2013 to 2025). A primary or metastatic malignant neoplasm involving the cervix. "Even though our study showed that SPP1, LYZ, and MCM5 have good clinical value and diagnostic performance in patients with cervical cancer and RA, there are still certain limitations." (PMID 41384115, 2025). "MCM5 is associated with genomic instability, and its high expression can lead to abnormal proliferation of cervical cancer, liver cancer." (PMID 41384115, 2025). "The results showed that SPP1, LYZ, and MCM5 not only had high diagnostic potential in patients with RA and cervical cancer but also showed specific binding sites with HPV 16 E6/E7 proteins through molecular docking simulation." (PMID 41384115, 2025). "Immunohistochemistry results further verified the high expression of SPP1, LYZ, and MCM5 in patients with RA combined with cervical cancer." (PMID 41384115, 2025). "Compared with cervical cancer patients, SPP1 (p = 0.005), LYZ (p = 0.005) and MCM5 (p = 0.006) were also highly expressed in RA combined with cervical cancer, and the difference was statistically significant." (PMID 41384115, 2025). "This study successfully identified SPP1, LYZ, and MCM5 as key hub genes for the comorbidity of RA and cervical cancer." (PMID 41384115, 2025). "On this basis, we successfully identified three hub genes (SPP1, LYZ, and MCM5) that were differentially expressed in the prognosis of RA and cervical cancer." (PMID 41384115, 2025). "Cox regression analysis identified 35 genes independently associated with the prognosis of cervical cancer, of which SPP1, LYZ, and MCM5 were significantly regulated in both RA and cervical cancer." (PMID 41384115, 2025). "Using RT‐PCR analysis, except for MCM3 and MCM5, MCMs are upregulated in cervical cancer in vitro and in vivo, which are critical in tumor progression." (PMID 36776764, 2023). "Mini chromosome maintenance protein 5, MCM5, which overexpressed protein in cervical cancer, was detected at a sensitivity of < 3 pM using a GNP-based electrode which is immobilized with capture antibody against MCM5." (PMID 38112935, 2023). "MCM5 overexpression has been discovered in some human cancers containing cervical cancer, bladder cancer, and so on." (PMID 35401213, 2022). "MCM5, a minichromosome maintenance protein, is upregulated in cervical cancer and promoted cell proliferation." (PMID 34530829, 2021). "Some recent studies have found that miR-362 acts as a tumor suppressor miRNA for cervical cancer by targeting MCM5 and other potential targets." (PMID 32582765, 2020). "By performing intersection analysis on 35 cervical cancer prognosis related genes and RA differential genes, a total of 3 co-upregulated differential genes were identified, namely SPP1, LYZ, and MCM5, which were upregulated in patients with rheumatoid arthritis and cervical cancer." (PMID 41384115, 2025). "MCM5, as a critical cell cycle regulator and DNA replication licensing element, was expressed highly in multiple cancer tissues, such as cervical adenocarcinoma, cervical cancer, renal cell carcinoma, and laryngeal squamous cell cancer." (PMID 36479666, 2023). "The increased level of MCM5 has been found in various cancers, including lung cancer, malignant skin diseases, gastric adenocarcinoma, bladder cancer, oral squamous cell carcinoma, and cervical cancer." (PMID 34993142, 2021). "Other functional biomarkers investigated in cervical cancer include markers of squamous differentiation cytokeratin (CK), cell cycle markers such as p21, p27, MCM5, cyclin A, cyclin E and cyclin D, and other molecules such as telomerase, involucrin, and survivin." (PMID 24260536, 2013). "Genes, such as MCM3, MCM5, MCM7, and DSN1, are associated with the pathogenesis of various cancers, such as salivary gland cancer, cervical cancer, and hepatocellular carcinoma, through regulation of cell cycle, but these genes may be involved in progression of BRCA." (PMID 31311202, 2019).
cervical cancer (continued). "The findings showed that cervical cancer tissues had increased expression levels of SPP1 (p = 0.047), LYZ (p = 0.034), and MCM5 (p = 0.002) in comparison to the healthy control group; this difference was statistically significant." (PMID 41384115, 2025). "Future studies should focus on collecting patients with RA and cervical cancer for high throughput sequencing to further reveal the role of SPP1, LYZ, and MCM5 in the disease." (PMID 41384115, 2025). "Meanwhile, the overexpression of MCM4, MCM5, MCM6, MCM10 and RECQL4 mRNA has been reported as a poor prognostic indicator in cervical cancer." (PMID 29463213, 2018). "Our data indicates the role of MCM4, MCM5, MCM6, MCM10 and RECQL4 in the progression of cervical cancer." (PMID 23874974, 2013). "Furthermore, we explored the molecular mechanism of comorbidity between RA and cervical cancer by immunohistochemistry analysis of patients with cervical cancer combined with RA, and successfully identified three key hub genes: SPP1, LYZ, and MCM5." (PMID 41384115, 2025). "Next, we evaluated the three genes’ potential for diagnosis, SPP1, LYZ, and MCM5, in the RA test set data (GSE55235, GSE55457, and GSE77298) and validation set (GSE89408) as well as the cervical cancer test data sets (TCGA and GTEx) and validation set (GSE63514)." (PMID 41384115, 2025). "Interestingly, levels of members of the Minichromosome Maintenance (MCM) family (MCM2, MCM3, MCM4, MCM5, MCM6, MCM7) were found to be highly significantly increased in cervical cancer tissue from early and late stage patients as compared to healthy tissue." (PMID 29719595, 2018). "Meanwhile, deletion of MCM5 also could not effect cell proliferation but makes cervical cancer cells vulnerable to RS such as HU or aphidicolin." (PMID 36776764, 2023).
lung carcinoma (13 papers, 2017 to 2025). "The mRNA expression of MCM5 (p = 0.008) was closely linked to worse OS in patients with lung cancer." (PMID 35360518, 2022). "MCM5 was overexpressed in lung cancers, and elevated MCM5 expression was associated with increased morbidity." (PMID 34490114, 2021). "Furthermore, we revealed that the arm-level gain of MCM5 was significantly associated with immune cell infiltration levels in lung cancer." (PMID 35360518, 2022). "Correlation analysis between the MCM2-10 expression and OS revealed that only MCM5 was closely related to poor OS in patients with lung cancer." (PMID 35360518, 2022). "MCM5 was highly expressed in patients with lung cancer and was closely related to TNM stage, pathological stage, sex, age, smoking status, primary therapy outcomes, and OS, PFI, and DSS events." (PMID 35360518, 2022). "MCM5 was positively correlated with the infiltration levels of Th2, NK CD56dim, Tgd, and Treg cells in lung cancer." (PMID 35360518, 2022). "The TIMER online tool was used to investigate the correlation between the MCM5 expression and immune cell infiltration in lung cancer." (PMID 35360518, 2022). "The influence of MCM5 on the prognosis of lung cancer patients was related to LUAD, smoking, pathologic stage, and TNM stages." (PMID 35360518, 2022). "Our findings demonstrated that MCM2-8 and 10 were highly expressed in lung cancer, and only MCM5 affected the prognosis of patients with lung cancer." (PMID 35360518, 2022). "Our results showed that the expression level of MCM5 in lung cancer tissues was significantly higher than that in normal tissues, and high MCM5 expression is significantly correlated with poor OS." (PMID 33936158, 2021). "In lung cancer, MCM5 interacted with histone deacetylase 1 (HDAC1) to aggravate cancer progression." (PMID 40695783, 2025). "MCM5 can aggravate the HDAC1-mediated malignant progression of lung cancer." (PMID 36479666, 2023). "Importantly, the molecular regulation of BCL6 on preRC genes, such as MCM5 was functional and linked to clonogenic growth of KRAS-mutant lung cancer cells." (PMID 36377663, 2022). "MCM5 was also highly expressed in many tumors, such as thyroid cancer cells and breast cancer, but its expression status and prognostic value in lung cancer have yet to be evaluated." (PMID 33936158, 2021). "In addition, the overexpression of MCM5 can promote the proliferation and invasion of lung cancer cells." (PMID 34993142, 2021). "MCM5 may serve as an adverse prognostic biomarker for lung cancer." (PMID 36479666, 2023). "GSEA for different expression levels of MCM4, MCM5 and MCM8 indicated that significant correlation of the genes with lung cancer progression and survival." (PMID 31323040, 2019). "On the other hand, MTL5 may positively regulate the expression of DNA replication licensing factors such as MCM5 and MCM7 in lung cancer." (PMID 35249447, 2022). "In lung cancer, high expression levels of MCM2, MCM5, MCM6, and MCM7 could be useful prognostic markers." (PMID 31514295, 2019). "Although MCM2 and MCM5 both play as the DNA entry gate of the MCM complex to regulate the initiation of DNA replication and might be important in regulating lung cancer, we only focused on studying MCM2." (PMID 29038488, 2017). "Notably, AS-IV significantly upregulates MCM5 in both lung cancer cells and tissues; MCM5 and HDAC1 facilitate the proliferation and migration of lung cancer cells, whereas AS-IV restores the expression of E-cadherin, hence suppressing lung cancer cell activity." (PMID 39064966, 2024).
bladder cancer (11 papers, 2010 to 2025). "MCM5 performed better in primary bladder cancer diagnosis, with a sensitivity of 74% and a specificity of 78%, making it a potentially helpful tool for symptomatic patients undergoing initial examination." (PMID 40282460, 2025). "In an earlier proof-of-concept study we showed that elevated Mcm5 levels in urine cell sediments are highly predictive of bladder cancer." (PMID 22792272, 2012). "In a proof-of-principle study we previously showed that elevated Mcm5 levels in cells in urine sediments is predictive of the presence of bladder cancer." (PMID 22792272, 2012). "The aim of this study was to evaluate Mcm5 as a biomarker for detection of bladder cancer alone, in comparison and in combination with NMP22." (PMID 22792272, 2012). "Elevated levels of MCM5 in urine sediment can be used to strongly predict bladder cancer." (PMID 34475953, 2021). "Indeed the degree of expression of Mcm2 and Mcm5 has been shown to predict recurrence and death in patients with bladder cancer." (PMID 22792272, 2012). "Interestingly, in a study of Mcm5 as a biomarker for bladder cancer, 12 patients presenting with haematuria were identified with a new diagnosis of prostate cancer." (PMID 20648010, 2010). "We could use the urinary content of hTERT, SENP1, PPP1CA, and MCM5 to detect bladder cancer recurrence." (PMID 21106093, 2010). "Next, we performed the survival analysis of these eight genes (ACTA2, CDH1, CCNB1, FLNA, MCM5, MAD2L1, TAGLN and TPM1) in bladder cancer." (PMID 37274283, 2023). "Potential downstream targets/pathways of ER signaling in bladder cancer cells were also identified and included ERK (activated by E2), AKT (via ERα), and minichromosome maintenance complex component 5 (MCM5) involving the initiation of DNA replication (via ERβ)." (PMID 40486871, 2025). "MCM5 combined with other urinary markers, such as NMP22 and UroVysion, can significantly enhance its clinical usefulness and result in a less expensive and more sensitive bladder cancer diagnosis and monitoring procedure." (PMID 40282460, 2025).
breast carcinoma (10 papers, 2007 to 2025). "MCM5 (minichromosome maintenance complex component 5) is considered to be a specific target for the gene therapy and a biomarker associated with the relapse-free survival of breast cancer patients." (PMID 33378415, 2020). "MCM5 (minichromosome maintenance complex component 5) has been recently found overexpressed in breast cancer patients." (PMID 35954483, 2022). "Consistently, BIRC5, E2F2, FOXM, and MCM5, showed higher expression in breast cancer tissues than in normal tissues, according to the immunohistochemical assessment from HPA database." (PMID 31579605, 2019). "Although 1222 target genes of miR-10b-5p were predicted and 48 significantly negatively correlated genes were obtained, only 5 overlapped genes, BIRC5, E2F2, KIF2C, FOXM1, and MCM5, were considered as potential key targets of miR-10b-5p in breast cancer for further analysis." (PMID 31579605, 2019). "Finally, 6 genes (GOLGB1, TMEM158, CXCL8, MCM5, HIF1AN, and TSPAN31) were selected that could optimally predict the lung metastasis risk of breast cancer patients." (PMID 33378415, 2020). "A previous study reported the observation that MCM2, MCM5 and CDC45 proteins are all downregulated in DDX5-depleted breast cancer cells; however, the role of the direct interaction between DDX5 and MCM5 in the regulation of MCM5 levels is presently unclear." (PMID 35954483, 2022). "Transcript levels of five of the seven metabolic genes (TALDO1, GPI, SHMT2, LDHA, and ADK: 5-gene metabolic signature) and six oncogenes: TAGLN2, NOLC1, HSP90AB1, HDGF, MCM5, and NCL, were elevated in TNBC patients when compared to patients with ER+ breast cancer." (PMID 34711841, 2021).
colorectal cancer (8 papers, 2018 to 2025). A primary or metastatic malignant neoplasm that affects the colon or rectum. "Phase-separated DDX21 facilitates epithelial–mesenchymal transition (EMT) and metastasis by binding to the MCM5 gene locus in colorectal cancer." (PMID 39866844, 2025). "To further validate the RLBPs expression in two clusters, we performed immunohistochemistry (IHC) of MCM3 and MCM5 in colorectal cancer tissues." (PMID 36428700, 2022).
ovarian carcinoma (7 papers, 2007 to 2025). A malignant neoplasm originating from the surface ovarian epithelium. "Previous studies showed that MCM5 was upregulated in cervical and ovarian cancers and was associated with their prognosis." (PMID 40695783, 2025). "The AUC of 0.68 for differentiating ovarian cancer from benign disease was pointed out for the urine minichromosome maintenance complex component 5 (MCM5) protein concentration." (PMID 38275400, 2024). "The aim of this study was to determine the sensitivity of MCM5 as a biomarker for the detection of endometrial and ovarian cancer." (PMID 33059604, 2020). "However, and in keeping with our previous observations in muscle-invasive urothelial carcinomas, median values of MCM-5 were significantly higher than those of Ki-67 in ovarian carcinomas as well as in LMP tumours." (PMID 17940502, 2007). "Microliposome maintenance (MCM) 2, MCM3, MCM4, MCM5, MCM6, and MCM7 are DNA replication regulators and are involved in the progression of multiple cancer types, but their role in ovarian cancer is still unclear." (PMID 34178669, 2021). "The sensitivity and specificity of urinary MCM5 is not currently high enough to warrant further testing of this biomarker for ovarian cancer detection." (PMID 35166350, 2022).
hepatocellular carcinoma (6 papers, 2019 to 2025). A malignant tumor that arises from hepatocytes. "YTHDF2 stabilizes the transcription of maintenance protein 2 (MCM2) and maintenance protein 5 (MCM5) in microchromosomes, promoting hepatocellular carcinoma progression in hepatitis B virus-infected individuals." (PMID 38711079, 2024). "Furthermore, miR‐214 targets overexpression of MCM5 and MCM7 in hepatocellular carcinoma (HCC) cells to inhibit cell replication and colony formation." (PMID 36776764, 2023). "In an HBV-related hepatocellular carcinoma (HCC) model, YTHDF2 stabilizes MCM2 and MCM5 transcripts in an m6A-dependent manner." (PMID 40271153, 2025).
melanoma (5 papers, 2015 to 2024). A malignant, usually aggressive tumor composed of atypical, neoplastic melanocytes. "In the present study, we found that MCM5 was upregulated in melanoma compared with its expression in normal skin and that increased expression of MCM5 was significantly associated with poor OS of patients with SKCM." (PMID 34490114, 2021). "A similar study on BRAFV600E inhibitor-addicted melanoma cells revealed downregulation of MCM2, MCM3 and MCM5 upon drug withdrawal in correlation with reduced cell viability ensuing from discontinued drug treatment." (PMID 37106808, 2023). "High mRNA levels of MCM4, MCM5, and MCM10 were closely related to worse prognosis in patients with melanoma." (PMID 34490114, 2021).